DNMT3A (DNA methyltransferase 3 alpha)
Diseases named in the same sentence as DNMT3A in open-access papers (continued):
Sharing a sentence is not in itself a finding about the gene and the disease.
cervical carcinoma (16 papers, 2015 to 2025). A carcinoma arising from either the exocervical squamous epithelium or the endocervical glandular epithelium. "CH-related mutations in DNA Methyltransferase 3 Alpha (DNMT3A) were most frequent in cervical cancers (5.9%)." (PMID 35725812, 2022). "Knocked-down DNMT3A in cervical cancer cells caused a decreasing of HAVCR2 and LGALS9 methylation level, accompanied by the expression of Tim-3 and galectin-9 elevated." (PMID 32699524, 2020). "For instance, overexpression of miR-182 inhibits DNMT3A expression and promotes apoptosis in C4-II cervical cancer cells; however, re-expression of DNMT3A reverses this effect." (PMID 41226543, 2025). "In cervical cancer, DNMT3A and DNMT3B regulated the methylation of p16 promoter, and affected its expression." (PMID 39284825, 2024). "For example, miR-331-3p repressed the expression of DNMT3A in cervical cancer cells by binding to DNMT3A mRNA." (PMID 39161894, 2024). "EZH2-H3K27me3/DNMT3A-DNA methylation regulates the expression of Tim-3 and galectin-9 in HPV18-associated cervical cancer." (PMID 36766706, 2023). "Tim-3 and galectin-9 are overexpressed in cervical cancer tissues, this biological effect is mediated through the aberrant epigenetic of Tim-3 and galectin-9, which is facilitated by the recruitment of DNMT3A to their promoter regions." (PMID 32699524, 2020). "In summary, the present study highlights the role of SUV39H1 and DNMT3A in the DNA methylation regulation of Tim-3 and galectin-9 in cervical cancer." (PMID 32699524, 2020). "Collectively, these results indicated that SUV39H1 participate in the regulation of DNMT3A through changing H3K9me3 expression level in cervical cancer cells." (PMID 32699524, 2020). "SUV39H1 targeted DNMT3A by increasing the level of H3K9me3 at the DNMT3A promoter region so that repressed Tim-3 and galectin-9 expression by DNA methylation in cervical cancer." (PMID 32699524, 2020). "Taken together, above results revealed that SUV39H1 regulated the expression of DNMT3A through elevating H3K9me3 level at the DNMT3A promoter in cervical cancer cells." (PMID 32699524, 2020). "SUV39H1 up-regulates H3K9me3 expression at the DNMT3A promoter region, which in turn induced expression of DNMT3A in cervical cancer." (PMID 32699524, 2020). "In the HeLa cervical cancer cell line, it has been reported that DNMT3a and 3b are the proteins most strongly reduced by zebularine." (PMID 25799509, 2015). "Here, we identified a novel function of SUV39H1 regulates DNMT3A expression through elevating H3K9me3 level at the DNMT3A promoter region, which could mediate Tim-3 and galectin-9 expression through DNA methylation in cervical cancer." (PMID 32699524, 2020). "In a similar manner, miR-29a downregulates DNMT3A and DNMT3B expression in HeLa and C-33A cervical cancer cells, which results in the demethylation and subsequent upregulation of p16." (PMID 41226543, 2025). "DNMT3A mediated the methylation of the CpG island at the promoter of LIMS2, and thus diminishing the expression of LIMS2 in cervical cancer cells." (PMID 39161894, 2024). "Tim-3 and galectin-9 are overexpressed in cervical cancer cases, which is mediated through the hypomethylation of HAVCR2 and LGALS9 because of the lesser expression and recruitment of DNMT3A to their promoter regions." (PMID 36766706, 2023). "DNMT3A involved in the induction of genes expression by directly binding to the HAVCR2 and LGALS9 promoter regions, suggested that DNMT3A participate in the epigenetic regulation of HAVCR2 and LGALS9 in cervical cancer." (PMID 32699524, 2020). "Targeting EZH2 or DNMT3A and CCL22-CCR4 axis may impede the progression or metastasis of cervical cancer and enhance patient prognosis." (PMID 39513112, 2024).
cervical carcinoma (continued). "After have been determining the baseline levels of DNA methylation on HAVCR2 and LGALS9 promoter regions among cervical cancer cell line, evaluation whether SUV39H1 mediated DNA methylation through DNMT3A is required for HAVCR2 and LGALS9 transcription." (PMID 32699524, 2020).
coronary heart disease (15 papers, 2019 to 2026). "These patients are at an increased risk of ischemic heart disease, with DNMT3A and PPM1D mutations being the most common alterations." (PMID 38162500, 2023). "CHIP-associated DNMT3A mutation was associated with a hazard ratio of 1.7 for coronary artery disease while TET2 mutation conferred a hazard ratio of 1.9." (PMID 33861346, 2021). "Clonal hematopoiesis, often caused by mutations in DNMT3A and TET2, is associated with blood cancer and coronary artery disease." (PMID 36097025, 2022). "Furthermore, the trial identified specific mutations in DNMT3A, TET2, ASXL1, and JAK2 as independent contributors to heightened coronary heart disease risk." (PMID 41458386, 2025). "Except for coronary heart disease, traditional cardiovascular risk factors, such as a history of AIS/TIA, hypertension, diabetes mellitus, and hypercholesterolemia, were not significantly different between DNMT3A‐driven CHIP carriers and non‐DNMT3A carriers." (PMID 39006763, 2024). "Nested case–control analyses of prospective cohorts, that together enrolled 4726 participants with coronary artery disease and 3529 controls, revealed that carriers of CHIP (DNMT3A, TET2 and ASXL1 mutations) have a risk of coronary artery disease that is substantially greater than controls." (PMID 33861346, 2021). "In a study that included subjects with coronary heart disease and controls, each major CHIP‐driving mutations, DNMT3A, TET2, ASXL1, and JAK2, was associated with an increased risk of coronary heart disease, but the hazard ratio was the lowest for the DNMT3A mutation." (PMID 36807865, 2023). "This multicenter study randomized approximately 28 individuals with known coronary artery disease and TET2 or DNMT3a CHIP to different combinations of DFV890, MAS825, and placebo, administered for 12 weeks, with a 30-day follow up." (PMID 39352379, 2024).
acute leukemia (14 papers, 2012 to 2026). A clonal (malignant) hematopoietic disorder with an acute onset, affecting the bone marrow and the peripheral blood. "This is in keeping with low proportions of DNMT3A mutations in pediatric acute leukemia and with high proportion of DNMT3A alterations in age-related clonal hematopoiesis of indeterminate potential." (PMID 27242978, 2016). "In the present study, PCR and direct sequencing was performed to analyze mutations of DNMT3A amino acid residue 882 in 99 acute leukemia patients, including 57 AML patients, 41 ALL patients and a single biphenotypic acute leukemia (BAL) patient." (PMID 23946816, 2013). "In addition, HOTAIR has been revealed to be correlated to upregulated Dnmt3a and Dnmt3b via the regulation of the DNA methylation in acute leukemia patients, contributing to the induced occurrence of acute leukemia." (PMID 31168296, 2019). "However, TET2- and DNMT3A KO mice responded differently to even the same cooperating mutations: when combined with Flt3ITD mutation, TET2 KO mice died more rapidly of mostly MPNs, while DNMT3A KO mice survived longer but eventually developed mixed phenotype acute leukemia." (PMID 36675240, 2023). "In acute leukemia (AL) patients, the expression of HOTAIR and its multiple downstream genes, including EZH2, lysine demethylase 1 (LSD1), DNA methyltransferase 3 alpha (DNMT3A), and DNMT3B, are also significantly increased." (PMID 31480503, 2019). "In our animal model, we could not find an acute leukemia transformation in Kmt2a-PTD mice with DNMT3A-MT, but we observed hematologic abnormalities with shorter latency and hepatosplenomegaly compared to control or DNMT3A-WT mice." (PMID 32015320, 2020).
glioblastoma (14 papers, 2014 to 2025). The most malignant astrocytic tumor (WHO grade IV). "In summary, we show that downregulation of CBX7 in glioblastoma is caused by promoter hypermethylation that is mediated by DNMT1 and DNMT3A." (PMID 39988672, 2025). "In contrast, aberrant expression of DNMTs, for example, high expression of DNMT1 and DNMT3B and low expression of DNMT3A, has been reported in glioblastoma." (PMID 34214250, 2022). "Since recruitment of DNMT3A by the pmx‐1b isoform of PRRX1 leads to GIC differentiation through the epigenetic regulation of PROM1 gene expression, pmx‐1b and DNMT3A are potentially interesting targets for the treatment of glioblastoma." (PMID 34214250, 2022). "DNMT3A was shown to play a crucial role in the proliferation and differentiation of mouse NSCs; however, little is known about how DNMTs regulate the differentiation of glioblastoma cells." (PMID 34214250, 2022). "In glioblastoma-derived cell lines and glioblastoma tumor samples, the methylation of mature miR-181a-5p by the DNMT3A/AGO4 complex inhibits the recognition of its target mRNA BIM, a proapoptotic gene, also known as B-cell chronic lymphocytic leukemia/lymphoma (Bcl-2)-like 11 (BCL2L11)." (PMID 34282776, 2021). "Interestingly, the p50 subunit of the NF-κB transcription factor was reported to interact with Dnmt3a in a glioblastoma cell line." (PMID 27690235, 2016). "Overall, our findings reveal that DNA methyltransferases (DNMT1 and DNMT3A) mediate the hypermethylation of the CBX7 promoter, leading to its frequent downregulation in glioblastoma tissues and cell lines." (PMID 39988672, 2025). "In the present study, we showed that, among the three DNA methyltransferases, the silencing of DNMT3A maintained the expression of PROM1 and the number of CD133‐positive glioblastoma cells, even in the presence of BMP‐4." (PMID 34214250, 2022). "A previous study showed that Dnmt1, Dnmt3a, and Dnmt3b can regulate the methylation status of BIRC5 in glioblastoma multiforme." (PMID 35664300, 2022). "Additionally, our study revealed that DNMT1 and DNMT3A mediate the hypermethylation of the CBX7 promoter, leading to its frequent silencing in glioblastoma cell lines and primary tumor tissues." (PMID 39988672, 2025). "A DNA methyltransferase 3A (DNMT3A)/AGO4 complex abolished miR-181-5p inhibition of gene expression via the cytosine methylation of miR-181-5p and resulted in an aggressive outcome of a glioblastoma multiforme (GBM)." (PMID 34068010, 2021).
chronic myelomonocytic leukemia (13 papers, 2012 to 2024). A myelodysplastic/myeloproliferative neoplasm which is characterized by persistent monocytosis, absence of a Philadelphia chromosome and BCR/ABL fusion gene, fewer than 20 percent blasts in the bone marrow and blood, myelodysplasia, and absence of PDGFRA or PDGFRB rearrangement. "After an extensive workup, he was diagnosed with AML/CMML (chronic myelomonocytic leukemia) with a normal karyotype with DNMT3A, CBFB, and PTPN11 mutations." (PMID 35656122, 2022). "Although patients with DNMT3A mutations show hepatosplenomegaly and lymphadenopathy due to extramedullary chronic myelomonocytic leukemia (CMML) compared with patients with WT DNMT3A; the signaling pathways that induce such profound hematopoietic dysregulation are poorly understood." (PMID 36976647, 2023). "The mutation rates for DNMT3A and TET2 in either gene or both were as high as 92.9% in angioimmunoblastic T cell lymphoma, 80% in chronic myelomonocytic leukemia, 58.4% AML with mutated NPM1 and 57.1% in peripheral T cell lymphoma." (PMID 34039392, 2021). "In our previous study, we established a bone marrow transplantation mouse model with DNMT3A R882H and a DNMT3A R878H conditional knock-in mouse model, which induced chronic myelomonocytic leukemia and AML, respectively." (PMID 34067359, 2021). "We also searched for TET2, DNMT3A, ASXL1, EZH2, IDH1/2 and CBL gene families mutations, given their potential clinical importance in diseases closely associated with SM like primary myelofibrosis, chronic myelomonocytic leukemia (CMML) and others." (PMID 22905207, 2012). "In addition, Dnmt3a loss can collaborate with gain of function mutant c-kitD814V to induce B-ALL, T-ALL, and mastocytosis with myeloid blasts, and with KrasG12D/+ to promote progression of juvenile and chronic myelomonocytic leukemia (CMML)." (PMID 27563627, 2016).
depression (13 papers, 2016 to 2025). "In the depression susceptible model, we found a continual decrease in the DNA modifying proteins (Dnmt3a, Tet2, and Tet3) while resilient animals display TDG returning to baseline." (PMID 37228107, 2023). "Of particular interest, the DNA modifying proteins Dnmt3a, Tet2, and Tet3 were found, suggesting that the loss or reduced expression of epigenetic machinery could be a key contributor to stress-induced depression." (PMID 37228107, 2023). "In our lab’s preliminary research, we observed that in a maternal separation-induced depression mouse model, Dnmt3a expression decreased in the hippocampus while increasing in the medial prefrontal cortex compared to control mice." (PMID 39268349, 2024). "Our results demonstrate that Venlafaxine is more effective than BAY K 8644 in ameliorating depression like behaviors and increasing Dnmt3a expression while decreasing GFAP expression." (PMID 39268349, 2024). "In our study, we observed reduced Dnmt3a expression levels in the hippocampal DG region of mice with LPS-induced depression compared to control mice." (PMID 39268349, 2024). "The different sensitivities of mice to depression were determined by the expression of Dnmt3a in the nucleus accumbens." (PMID 33101076, 2020). "In another study that employed a subchronic variable stress paradigm to produce a depression-like phenotype, female mice had increased levels of Dnmt3a within the nucleus accumbens." (PMID 27746953, 2016). "Additionally, variations in Dnmt3a expression in the ventral hippocampus of mice can play distinct roles in the development of depression in both males and females." (PMID 39268349, 2024). "Furthermore, in our depression susceptible model where 5hmC continuously decreased along the ASDS-CSDS-LSDS continuum, the DNA modifying proteins Dnmt3a, Tet2, and Tet3 were found." (PMID 37228107, 2023). "This discrepancy may reflect the different depression models and behavioral tests used under the same depression umbrella, but it also indicates the significance of DNMT3A in all the models." (PMID 33101076, 2020). "The expressions of Dnmt3a in this region were also investigated in depression models." (PMID 33101076, 2020). "Several studies have shown a causal relationship between Dnmt3a and depression, but the results are not consistent." (PMID 33101076, 2020). "Mice with a knock-out of Dnmt3a in the nucleus accumbens showed resilience to the subchronic variable stress, providing further support for the concept that Dnmt3a overexpression might mediate stress-induced depression." (PMID 27746953, 2016). "However, Dnmt1 knockout (KO) mice displayed an anxiolytic and anti-depression phenotype, while Dnmt3a deficiency does not alter behavior, which indicated Dnmt1 and Dnmt3a played distinct roles in controlling emotion in mice." (PMID 33171840, 2020). "Chronic stress has been shown to increase DNMT1 and DNMT3a levels in the nucleus accumbens and treatment with DNMT inhibitors reversed depression-like behaviors." (PMID 34276306, 2021). "However, one study suggests DNMT3B may also change in depression, paralleling DNMT3A." (PMID 33101076, 2020). "In summary, given the contradictory observations among the studies of DNMT3A and DNMT3B in depression patients and depression-like animal models, it is still early to draw a conclusion based on the available data." (PMID 33101076, 2020). "CSDS-induced depression-like behaviors are accompanied by an increase in the Dnmt3a levels in the NAc, suggesting that CSDS-induced depression-like behaviors are positively correlated with increased spine density in the NAc neurons." (PMID 26881133, 2016). "In another study, the DNMT3B expressions in the dorsolateral prefrontal cortex of depression patients were increased, and the DNMT3A expressions showed no change compared to those in healthy controls." (PMID 33101076, 2020).
depression (continued). "Therefore, our results demonstrated that DNMT1 and DNMT3a regulate the level of DNA methylation in the CRMP2 gene promoter region, thus affecting the expression of CRMP2 in the hippocampus of rats and participating in the pathogenesis of depression." (PMID 33815064, 2021). "Since different brain areas may play different roles in the pathogenesis of depression, it is not surprising that Dnmt3a alterations are different in these areas." (PMID 33101076, 2020). "However, it seems that DNMT3a and DNA hypomethylation in the mPFC are not involved in the development of PTX‐induced depression." (PMID 39679872, 2025).
VEXAS syndrome (13 papers, 2022 to 2025). An adult-onset inflammatory disease that affects only males and is caused by somatic, not germline, mutations. "In one study, DNMT3A mutation was seen in 47.4% with VEXAS syndrome: TET2 in 20.0% and ASXL2 in 13.3%." (PMID 36879894, 2023). "To understand DNMT3A-mutated (mtDNMT3A) clones in the context of VEXAS syndrome, we identified single cells expressing DNMT3A mutations from mRNA sequencing." (PMID 37586319, 2023). "In addition, the hyperinflammatory microenvironment in VEXAS syndrome likely does positively select other somatically mutated clones: DNMT3A and TET2 clones are frequent in VEXAS18,19,20,21 as they are in other inflammatory clinical conditions." (PMID 37586319, 2023). "In particular, a loss-of-function of DNMT3A, which acts as a repressor of inflammation, may further contribute to the proinflammatory status of VEXAS syndrome." (PMID 36662445, 2023). "For patients with concurrent DNMT3A mutations, responses to azacytidine have been particularly favorable, suggesting that this mutation may serve as a predictive biomarker for treatment efficacy in VEXAS syndrome." (PMID 39598114, 2024). "We and others have identified isolated CH mutations, predominantly in DNMT3A and TET2, in 50% of MDS cases with VEXAS syndrome (6 out of 12 cases in total, DNMT3A mutation in 2, TET2 mutation in 2)." (PMID 38819628, 2025). "A diagnosis of VEXAS syndrome was established through genetic testing, which revealed variants in the UBA1 and DNMT3A genes following a collaborative multidisciplinary approach." (PMID 41450412, 2025). "Similar patterns of co‐occurring mutations in myeloid diseases have been reported, including DNMT3A, TET2 and SF3B1 in MDS and VEXAS syndrome." (PMID 41310823, 2025). "Next-generation sequencing (NGS) detected mutations in DNMT3A and UBA1, leading to a diagnosis of low-risk MDS (IPSS-R of 2) and VEXAS syndrome." (PMID 38398362, 2024). "Some VEXAS patients have been shown to have DNMT3A gene mutations, which could be the cause of the coexistence of hematologic malignancies like MDS in VEXAS syndrome patients." (PMID 38410307, 2024). "Clinically, although CH mutations did not affect phenotypic heterogeneity or disease severity of VEXAS syndrome, presence of either DNMT3A or TET2 mutations increased the risk of mortality by 2 to 14-fold." (PMID 38819628, 2025). "This correlation between DNMT3A mutations and improved response to azacytidine highlights the potential of DNMT3A as a biomarker that could guide therapeutic decisions in VEXAS syndrome." (PMID 39598114, 2024). "The use of the hypomethylating agent azacytidine in VEXAS syndrome has been also suggested as an effective treatment strategy, especially in patients with concomitant MDS, those without aplastic bone marrow and patients with a concomitant DNMT3A mutation." (PMID 36662445, 2023).